SREBF2 (sterol regulatory element binding transcription factor 2)
Diseases named in the same sentence as SREBF2 in open-access papers (continued):
Sharing a sentence is not in itself a finding about the gene and the disease.
diabetes (19 papers, 2012 to 2024). "Overexpression of sterol regulatory element-binding factor (Srebf2) in transgenic animals is linked to elevated cholesterol levels and diabetes development." (PMID 33066385, 2020). "Thus, the overexpression of Srebf1 and Srebf2 has been shown to cause beta cell dysfunction and eventually diabetes, which at the cellular level is reflected by the repression of Pdx1 expression, impaired insulin secretion and content, as well as cellular triglyceride and cholesterol accumulation." (PMID 36232358, 2022). "In addition, previous studies have shown that SREBF2 controls brain cholesterol synthesis and is involved in diabetes, which is associated with an increased risk of AD, and that AD model mice overexpressing SREBF2 show Aβ accumulation and neurofibrillary tangle formation." (PMID 31500627, 2019). "In conclusion, these results suggest a significant increase in HSP90AA1 and HSPA8 concomitant with diabetes, and SREBF2 and GTAT2 may regulate the expression of HSP90AA1 and HSPA8." (PMID 38166541, 2024). "For example, in our previous study we showed a 3-fold range of expression of Srebf2 and Hmgcr and a 2-fold range in synaptosomal cholesterol content in brains of 16 elderly humans with and without diabetes and dementia." (PMID 23585733, 2013).
hyperlipidemia (19 papers, 2011 to 2025). "Although the mechanisms by which infection and/or inflammation induce the upregulation of Srebf2 are not clear, our study suggests that additional mechanisms related to infection induce hyperlipidemia during infection." (PMID 22992388, 2012).
melanoma (19 papers, 2019 to 2025). A malignant, usually aggressive tumor composed of atypical, neoplastic melanocytes. "However, our data provide precise insights into cholesterol synthesis, showing that the expression of Scap, Srebf2 and Hmcgr was diminished in silenced melanoma cells." (PMID 37160873, 2023). "Additionally, SREBF2 can induce transferrin and inhibit ferroptosis in circulating melanoma cells." (PMID 40335466, 2025). "To evaluate potential activators of DNFA expression, we depleted SREBF1, SREBF2, and co-activators MED15 and CREBBP28 with siRNAs, and examined DNFA expression across three melanoma cell lines: HT-144, A375 and MEL-JUSO." (PMID 31316083, 2019).
ovarian carcinoma (19 papers, 2015 to 2025). A malignant neoplasm originating from the surface ovarian epithelium. "Additionally, ovarian cancer mutant cells/SREBF2-KD (SREBF2 disrupted using CRISPR technology) treated with paclitaxel in low, but not high serum or in presence of statin showed a significantly lower cell viability." (PMID 32577155, 2020). "We found that suppression of SREBF2 in ovarian cancers results in down-regulation of cholesterogenic target genes such as the DHCR7, while induction of SREBF1 is associated with increased expression of lipid synthesis genes such as the SCD1, which was found highly elevated." (PMID 26807200, 2015). "Interestingly, in cisplatin-resistant ovarian cancer cells, the expression of FDFT1 was found to be increased by sterol regulatory element binding transcription factor 2 (SREBP2)." (PMID 35008958, 2022). "We found that both SREBF2 and its target gene DHCR7 are downregulated in ovarian cancer tissues." (PMID 26807200, 2015).
Insulin resistance (18 papers, 2013 to 2025). Increased resistance towards insulin, that is, diminished effectiveness of insulin in reducing blood glucose levels. "In particular, kernel causality analysis revealed a causal effect of the abundance of Enterobacteriaceae on SREBF2 upregulation and of the surrogate markers of insulin resistance on NAFLD activity in the HC group." (PMID 35634707, 2022). "Expression of the transcription factor SREBF2, which regulates expression of genes involved in cholesterol synthesis, which is associated with insulin resistance, was decreased in G4+/− HF IU fetal liver compared with G4+/− C IU." (PMID 23690974, 2013). "Comorbidities, such as insulin resistance/T2DM, hypertension, and inflammatory processes can also mask the real impact of SREBF1c and SREBF2 polymorphisms on plasma lipids." (PMID 31490983, 2019). "All these data may indicate that S-mice seem to be more protected against insulin resistance on a HFHS diet and overexpression of Srebf2." (PMID 33066385, 2020).
viral infection (16 papers, 2012 to 2026). "However, a recent report showed that miR-342 is upregulated following viral infection and induces a coordinate reduction in the abundance of many genes in the sterol biosynthesis pathway, including its master regulator SREBF2, as well as HMGCR as we showed herein." (PMID 34322524, 2021).
liver cancer (13 papers, 2017 to 2025). An epithelial or non-epithelial malignant neoplasm that arises from the liver. "The study employed TCGA and GEO databases to investigate the expression of SREBF2 and autophagy‐related proteins in liver cancer." (PMID 40476478, 2025). "The results of hepatitis B‐related liver cancer data analysis suggested higher expression of SREBF2 and autophagy indicators in cancerous tissues than in adjacent tissues." (PMID 40476478, 2025). "SREBF2 expression is associated with a poor prognosis in T-cell lymphoma, AML, plasma cell myeloma and liver cancer." (PMID 36600891, 2022). "We confirmed the same tendencies for SREBF2, PCSK9 and HMGCR expression in three liver cancer cell lines (e.g., HepG2, Huh6 and Huh7) in comparison with the normal liver cell line THLE2." (PMID 36612001, 2022).
Hyperinsulinemia (11 papers, 2012 to 2025). An increased concentration of insulin in the blood. "Sustained hyperinsulinemia, a characteristic syndrome of IR, can promote the accumulation of liver cholesterol through the activation of the sterol regulatory element binding transcription factor 2 (SREBP-TF2)." (PMID 25103525, 2014).
glioma (9 papers, 2017 to 2025). A benign or malignant brain and spinal cord tumor that arises from glial cells (astrocytes, oligodendrocytes, ependymal cells). "Genes involved in the regulation of the mevalonate pathway (INSIG1 and SREBF2 but not SREBF1) were also downregulated in dense NHAs but not glioma cells." (PMID 28118603, 2017).
lung carcinoma (9 papers, 2019 to 2025). "Based on our findings, EHMT2 seems to directly regulate transcriptional expression of SREBF2, a master regulator for cholesterol biosynthesis, in effect lowering cholesterol in lung cancer." (PMID 32028644, 2020). "Moreover, USP28, SREBF2 and HMGCS1 were significantly upregulated in LSCC compared to LADC in tissue from a cohort of human lung cancer patients." (PMID 37202505, 2023). "Finally, Kaplan–Meier analysis of human lung cancer patient data revealed that both USP28 and SREBF2 were indicative of poor survival in a mixed cohort." (PMID 37202505, 2023).
Sepsis (9 papers, 2020 to 2025). Sepsis is defined as life-threatening organ dysfunction caused by a dysregulated host response to infection. "Hepatic gene expression of the main regulator of the cholesterol pathway, Srebf2, was increased by sepsis whereas hepatic cholesterol-synthesizing enzymes Hmgcs1 and Fdft1 were unaffected, and Aacs expression was decreased compared to healthy mice—all irrespective of 3HB treatment." (PMID 34274000, 2021).
Alzheimer disease (8 papers, 2018 to 2024). A progressive, neurodegenerative disease characterized by loss of function and death of nerve cells in several areas of the brain leading to loss of cognitive function such as memory and language. "The three TFs that have the highest cumulative weight in the models of these genes are SREBF1, SREBF2 and ZEB1, themselves associated with neuronal differentiation and neurodegenerative diseases like Alzheimer’s Disease or Huntington’s Disease." (PMID 38632500, 2024). "In early works, using APPswe/PSEN1dE1 mice overexpressing the sterol regulatory element-binding transcription factor 2 (SREBF2), we demonstrated that elevated brain cholesterol levels accelerate and worsen the pathological features of Alzheimer’s disease, including neuroinflammation." (PMID 39765769, 2024). "MEG3 (ENST00000398461)/hsa-let-7d-5p/ATF6B axis showed importance in Parkinson’s and late Alzheimer’s diseases, while AC092687.3/hsa-let-7e-5p/[SREBF2, FNIP1, PMAIP1] and SDCBP2-AS1 (ENST00000446423)/hsa-miR-101-3p/MAPK6 axes are probably related to Alzheimer’s disease development and pathology." (PMID 38027526, 2023).
lipid metabolism disorders (8 papers, 2015 to 2025). "Compared with the Control group, the mRNA expression of Srebf2, Scap, Hmgcr, Soat1, Npc1, Snai3, Twist1, Itgav, Vegfc, and Tgfbr1 has higher expression in model group, indicating that there is lipid metabolism disorder in model mice." (PMID 38724499, 2024).
schizophrenia (8 papers, 2009 to 2024). A major psychotic disorder characterized by abnormalities in the perception or expression of reality. "The association of polymorphisms in the SREBF1 and SREBF2 genes with schizophrenia was first reported in 2010 and has been replicated in three independent samples." (PMID 34575210, 2021). "In conclusion, we have confirmed that non-coding variants linked to the SREBF1 and SREBF2 genes are associated with increased risk of schizophrenia." (PMID 29720671, 2018). "A recent study found that polymorphisms in the SREBPF1 and SREBF2 genes are associated with schizophrenia, suggesting that variation in lipid biosynthesis affects disease susceptibility." (PMID 19715613, 2009). "We found that a subset of lipid-related genes was nominally associated with schizophrenia (p = 0.037), but this signal did not survive multiple testing correction (FWER = 0.16) and was mainly driven by the SREBF1 and SREBF2 genes that have already been linked to schizophrenia." (PMID 29720671, 2018). "It remains to be clarified whether variants in SREBF1 and SREBF2 influence the risk of schizophrenia through effects on lipid biosynthesis and myelination in the brain." (PMID 29720671, 2018). "Of note, among the 108 schizophrenia-associated genomic loci, one is on chromosome 22q13.2, which includes SREBF2 gene that encodes sterol regulatory element-binding protein 2 (SREBP2), the major transcription factor that regulates cholesterol biosynthesis." (PMID 33942715, 2021). "Since SREBF1 and SREBF2 on chromosome 17p11.2 and 22q13.2 have both been associated with schizophrenia, the GSEA analysis of the PGC2 schizophrenia GWAS data was re-run after exclusion of these genes." (PMID 29720671, 2018). "Moreover, the trend signal observed in this subset was mainly driven by variants in the well-known schizophrenia-associated genes SREBF1 and SREBF2." (PMID 29720671, 2018). "Several studies have reported the importance of SREBF1 and SREBF2 factors in the lipid biosynthesis and their possible involvement in antipsychotic drug effects and the genetic variants of SREBF1 and/or SREBF2 could affect schizophrenia susceptibility." (PMID 22348066, 2012).
glioblastoma (7 papers, 2018 to 2025). The most malignant astrocytic tumor (WHO grade IV). "This study identified six PMRGs (SARDH, ACHE, ADSL, PNPLA3, MAPK1 and SREBF2) as potential prognostic biomarkers for glioblastoma." (PMID 40313243, 2025).
hypertriglyceridemia (5 papers, 2017 to 2024). A laboratory test result indicating elevated triglyceride concentration in the blood. "Patients carrying the A allele of the SREBF2 (rs2267443) gene were at an increased risk for hypertriglyceridemia (after adjustment for the multivariate analysis)." (PMID 34683084, 2021). "Nevertheless, our results provided evidence of an association between the SREBF2 rs2267443 (G/A) polymorphism and hypertriglyceridemia." (PMID 34683084, 2021). "The association of hypertriglyceridemia in patients with the SREBF2 rs2267443 (G/A) polymorphism remained significant after adjustment by multiple logistic regression (odds ratio = 4.47, 95% confidence interval = 1.62–12.32, p = 0.004)." (PMID 34683084, 2021). "Patients with the SREBF2 gene rs2267443 (GA + AA) genotype had a significantly higher incidence of hypertriglyceridemia as compared with the GG genotype (odds ratio = 2.56, 95% confidence interval = 1.12–5.99, p = 0.02)." (PMID 34683084, 2021). "Nonetheless, the SREBF2 rs2267443 (G/A) A-allele carriers were at a higher risk for hypertriglyceridemia, whereas the INSIG2 rs11123469 (T/C) C-allele carriers had a lower risk for hypertriglyceridemia, after being adjusted for clinical characteristics using multiple logistic regression." (PMID 34683084, 2021).
liver disease (5 papers, 2017 to 2025). "When the analysis was replicated in 39 independent liver samples from NAFLD obese patients, high transcription levels in CpG regions of zinc finger protein 274 (ZNF274), PGC1A, and sterol regulatory element binding transcription factor 2 (SREBP2) were associated with liver disease." (PMID 28250848, 2017).
myeloma (5 papers, 2022 to 2025). "To mechanistically confirm that SREBPs inhibition contributes to the anti-myeloma effects of SEL, we performed shRNA-mediated knockdown of SREBF1 and SREBF2 in MM cells, with knockdown efficiency confirmed by immunoblotting." (PMID 40229499, 2025).
neuroblastoma (5 papers, 2020 to 2023). Neuroblastoma (NB) is the most common solid, extracranial childhood tumor. "It is still unknown that whether the expression of the six genes, AR, SCAP, SREBF1, SREBF2, HMGCR, and CYP17A1 are closely associated with neuroblastoma patient survival." (PMID 34041015, 2021).
osteoarthritis (4 papers, 2012 to 2022). A noninflammatory degenerative joint disease occurring chiefly in older persons, characterized by degeneration of the articular cartilage, hypertrophy of bone at the margins and changes in the synovial membrane. "The expression of SREBF2 was upregulated in osteoarthritis and played an important role in the pathogenesis of this disease." (PMID 34806937, 2021). "After ATDC5 cells were induced by IL-1β, the expression of SREBF2 in osteoarthritis cells was detected by RT-qPCR." (PMID 34806937, 2021).
ZIKV infection (4 papers, 2022 to 2025). "ZIKV infection of moDCs was inhibited by knockdown of SREBF2, but not SREBF1, at least at the knockdown efficiencies achieved here, which suggests that DMHCA blocks ZIKV in part by inhibiting SREBP2 activation." (PMID 36097162, 2022).
renal carcinoma (3 papers, 2020 to 2023). A carcinoma arising from the epithelium of the renal parenchyma or the renal pelvis. "Among the most altered genes, it has been shown that renal cancer progression can be promoted by upregulation of CXCL8, ADAM9, NDRG1, SOD2, SREBF1 and SREBF2 genes." (PMID 35505422, 2022).
acute myocardial infarction (2 papers, 2008 to 2023). Necrosis of the myocardium, as a result of interruption of the blood supply to the area. "Interestingly, the SCAP 2386A>G genotypes were found to modify the association between SREBF-2 1784G>C and myocardial infarction (MI) in men." (PMID 19116028, 2008).
adrenoleukodystrophy (2 papers, 2016 to 2024). A peroxisomal disorder resulting in cerebral demyelination, axonal dysfunction in the spinal cord leading to spastic paraplegia, adrenal insufficiency and in some cases testicular insufficiency. "The PPARα agonist fenofibrate has also been shown to activate SREBF2 and to have therapeutic potential for the treatment of adrenoleukodystrophy, consistent with the possibility that this drug may stimulate myelination." (PMID 27462272, 2016).
breast tumors (2 papers, 2018 to 2020). "On the contrary, SREBF2 (1.02-fold change) was found to be highly expressed in breast tumours analysed by GEPIA, however, was found to be relatively under expressed as analysed by Oncomine." (PMID 32577155, 2020).
hepatoblastoma (2 papers, 2024 to 2025). Hepatoblastoma (HB) is a malignant hepatic tumor and is the most common pediatric liver cancer. "RT‐PCR analysis showed the increased expression of HB‐associated genes like AFP, GPC3, and DUSP9, indicating that SREBF2 could enhance hepatoblastoma stemness." (PMID 40271711, 2025). "We overexpressed SREBF2 in HepG2 cells to elucidate the role of SREBF2 in IGF2‐driven hepatoblastoma tumorigenesis." (PMID 40271711, 2025). "The role of SREBF2 in IGF2‐induced hepatoblastoma was further investigated by silencing SREBF2 in IGF2‐treated HepG2 cells." (PMID 40271711, 2025). "Hepatoblastoma exhibited significantly higher levels of cholesterol synthase (SREBF2, SQLE, HMGCS1) compared to normal liver tissues, which indicated higher metabolic activity." (PMID 40271711, 2025). "Western blot analysis showed that Fatostain treatment decreased the expression of HB‐associated genes like AFP, OCT4, GPC3, and DUSP9, indicating that SREBF2 inhibition could reduce hepatoblastoma stemness." (PMID 40271711, 2025). "Additionally, we simultaneously detected the expression levels of IGF2, SREBF2, DUSP9, and LDs in consecutive sections of 16 hepatoblastoma patient tissues." (PMID 40271711, 2025).
leukemia (2 papers, 2009 to 2024). A malignant (clonal) hematologic disorder, involving hematopoietic stem cells and characterized by the presence of primitive or atypical myeloid or lymphoid cells in the bone marrow and the blood. "Compared to PBMCs from healthy donors, both types of leukemia showed SREBF2 significantly upregulated, interestingly with the highest trend in KMT2Ar leukemia patients." (PMID 38030791, 2024).
migraine (2 papers, 2024 to 2025). "MR analysis of testicular tissue confirmed a significant causal relationship between the SREBF2 gene and migraine (OR = 1.10, 95% CI: 1.01–1.19, p < 0.05)." (PMID 40994718, 2025). "The MR analysis revealed a significant association between SREBF2 expression and the susceptibility to elevated migraine risk." (PMID 38840241, 2024). "REV1 may reduce the migraine risk by regulating DNA damage repair, while SREBF2 may increase the risk of migraine by regulating cholesterol metabolism." (PMID 38840241, 2024). "Cross-tissue TWAS analysis, along with validation through single-tissue TWAS and MAGMA, led to the identification of two migraine susceptibility genes (REV1 and SREBF2), which were further substantiated by MR and colocalization analyses." (PMID 38840241, 2024). "We sought to explore the potential interactions among SREBF2 or REV1 and previously identified genes associated with migraine susceptibility." (PMID 38840241, 2024). "Through cross-tissue TWAS analysis and rigorous validation, two genes (REV1 and SREBF2) associated with migraine risk were identified, which have not been previously reported." (PMID 38840241, 2024). "Lastly, the expression levels of REV1 and SREBF2 in tissues previously more closely associated with migraine, such as cerebral arteries, were not able to be assessed and validated in the current dataset." (PMID 38840241, 2024). "Therefore, further investigation is required to elucidate the role of SREBF2 and REV1 in migraine pathogenesis." (PMID 38840241, 2024).
non-alcoholic steatohepatitis (2 papers, 2020 to 2023). "Overexpression of Srebf2 increases lipotoxicity in different kind of cells, including PBCs and hepatocytes, inducing DM and non-alcoholic steatohepatitis." (PMID 33066385, 2020).
autoimmune disease (1 paper, 2025). A disorder resulting from loss of function or tissue destruction of an organ or multiple organs, arising from humoral or cellular immune responses of the individual to their own tissue constituents. "Notably, AtM B cells were also featured with the high expression of ZEB2, TBX21, and SREBF2, consistent with specific TFs of age-associated B cells (ABCs) in autoimmune diseases." (PMID 41459486, 2025).